FASN (fatty acid synthase)
Diseases named in the same sentence as FASN in open-access papers (continued):
Sharing a sentence is not in itself a finding about the gene and the disease.
breast cancer (continued). "In resistant breast cancer cells, increased FASN-catalyzed endogenous FA biogenesis was related to HER2 overexpression." (PMID 35646898, 2022). "Both ACSS2 and FASN contribute to acetate-dependent lipogenesis in aggressive breast cancer through hypoxia-inducible factor 1β (HIF1β)." (PMID 35178126, 2022). "Cancer cells can also rewire lipid metabolism to mediate the development of acquired drug resistance, while targeting lipid metabolic enzymes (e.g., fatty acid synthase) re-sensitize breast cancer resistant to HER2-targeted therapies." (PMID 35790992, 2022). "Focusing on breast cancer, concerning increased fatty acid (FA) synthesis, the limiting enzyme is fatty acid synthase (FAS), encoded by the FASN gene, which is known to have oncogenic functions." (PMID 35053485, 2022). "Inducing SREBP-1 gene to activate the Akt and HIF1 in breast cancer also increased the expression of FASN, which partly conduced to hypoxia-induced chemoresistance to cyclophosphamide." (PMID 35646898, 2022). "FASN expression can also be regulated by PI3K/AKT/mTOR and MAPK, whose inhibition reduces FASN expression in breast cancer cells." (PMID 35053485, 2022). "Reducing these with docosahexaenoic acid (DHA) abrogated insulin-stimulated FASN expression, suggesting insulin promotes FASN expression in breast cancer by upregulating SREBP through the Akt pathway." (PMID 35448537, 2022). "Proton pump inhibitors (PPIs) effectively suppressed FASN to induce apoptosis and sensitized to doxorubicin in breast cancer." (PMID 35646898, 2022). "The combinatorial roles of the FASN inhibitor and conventional chemotherapy in breast cancer and astrocytoma are being evaluated under clinical trials." (PMID 36428733, 2022). "Upregulated expression of FASN significantly increases FA production by de novo synthesis, leading to a deteriorated outcome of breast cancer." (PMID 35790992, 2022). "Here, we demonstrated the IGF-1/IGF-1R signaling axis to induce FASN protein and mRNA expression in breast cancer cells." (PMID 36096767, 2022). "In combination with a FASN inhibitor, trastuzumab resensitizes trastuzumab-resistant breast cancers by downregulating HER-2 expression." (PMID 36059650, 2022). "AF promoted apoptosis and suppressed proliferation of breast cancer cells by inhibiting the fatty acid synthase." (PMID 35635082, 2022). "Compound had effects on the gene expression and activity of fatty acid synthase (FASN) in the human breast cancer SK-BR-3 cell line, and apoptotic effects on breast cancer cells." (PMID 36364014, 2022). "Fatty acid synthase (FASN) is a key metabolic enzyme that dictates the terminal catalytic step in FA synthesis and promotes breast cancer metastasis." (PMID 35954428, 2022). "A previous study demonstrated that patuletin was able to inhibit FASN and showed antiproliferative and pro-apoptotic activities against human breast cancer cells." (PMID 36160439, 2022). "Studies have demonstrated that Food and Drug Administration (FDA)-approved proton pump inhibitors can effectively inhibit FASN and sensitize breast cancer cells to the doxorubicin and ionizing radiation therapy in a large breast cancer patient cohort." (PMID 35216362, 2022). "FASN overexpression is closely associated with acquired resistance to ADR and mitoxantrone in breast cancer and gemcitabine resistance in PDAC, respectively." (PMID 36359776, 2022). "Breast cancers overexpressing FASN are more likely to recur and metastasize and present significantly shorter disease-free and overall survival." (PMID 35433453, 2022). "Since MDA-MB-231 cells are triple negative breast cancer (TNBC) cells, we next asked if the IGF-1-SRPK2 axis modulated FASN protein expression in other breast cancer cell lines." (PMID 36096767, 2022). "FASN is overexpressed in breast carcinomas with over 70% of primary TNBC and in several other epithelial malignancies as demonstrated with immunohistochemistry." (PMID 35433453, 2022).
breast cancer (continued). "Through self-metabolic reprogramming, CAFs serve as hubs of lipids to support breast cancer cells growth with over-expression of FASN." (PMID 34888248, 2021). "Our findings gain novel insights into how PI3K inhibitors exert their activity by modulating the tumor-immune interaction, and provide a rationale for the concurrent targeting of PI3K and FASN inhibitor in breast cancer treatment." (PMID 34373258, 2021). "Enhanced of both expression and activity of FASN are considered early events in breast cancer progression and blocking FASN can induce antitumor effects in TNBC." (PMID 33808259, 2021). "A reduction in ACSL3, FASN and SCD mRNA expression has been observed across the different breast cancer cell lines and linked with fatty acid metabolism-associated genes." (PMID 34944852, 2021). "We first examined apoptotic cell death using the semi-synthetic FASNi C75 in three breast cancer cellular models expressing distinct levels of FASN: BT-474 »> MCF-7 > MDA-MB-231 (inset)." (PMID 34675185, 2021). "The stimulatory effects of estradiol on FASN gene promoter activity and protein expression were blunted by anti-estrogens in endocrine-responsive breast cancer cells." (PMID 33800852, 2021). "FASN phosphorylation levels between normal tissues and the corresponding tumor group were obtained, and six types of cancers (breast cancer, clear cell RCC, LUAD, ovarian cancer, colon cancer, and UCEC) were analyzed." (PMID 34879004, 2021). "A human breast cancer xenograft model evidenced that oral administration of the only clinically available FASNi drastically sensitizes FASN-addicted breast tumors to ineffective single-agents navitoclax and venetoclax in vivo." (PMID 34675185, 2021). "Fatty acid synthase (FASN) catalyzes palmitate biosynthesis using acetyl-CoA and malonyl-CoA in the presence of NADPH; FASN is overexpressed in treatment-resistant mammary tumors, and fatty acid syntheses are increased in brain metastases in mammary tumors." (PMID 34692471, 2021). "As for breast cancer progression specifically, several studies show that fatty acid synthase (FASN) inhibition decreases proliferation and increases the chemosensitivity of many breast cancer cell lines as well as in experimental breast cancer models." (PMID 34769312, 2021). "E2 or FUL treatment did not alter FASN levels in MCF-7 cells but upregulated FASN expression in hormone unresponsive MDA-MB-231 breast cancer cells." (PMID 34771486, 2021). "Previous studies have shown that fatty acid synthase (FAS), an enzyme that synthesizes fatty acids from acetic acid and malonyl-CoA, is associated with poor prognosis among patients with breast cancer." (PMID 34095320, 2021). "Others have shown that over-expression of FASN can be a predictive marker for cisplatin resistance and that inhibiting FASN can overcome cisplatin resistance in mice bearing breast cancer xenografts." (PMID 34298999, 2021). "FASN inhibition induced both autophagy and endoplasmic reticulum stress in human breast cancer cells." (PMID 34959709, 2021). "In LNCaP, MCF7 (human breast cancer cell), and A549 cell (human lung cancer cell), endogenous FASN protein levels were increased by USP14 knockdown contrary to the results in MPHs." (PMID 34948233, 2021). "Transcriptomic and proteomic data have confirmed that HER2+ breast tumors are the highest FASN-expressors among breast cancer subtypes." (PMID 34675185, 2021). "In a similar trend, both breast cancer cell lines showed different expression profiles against miR-33a treatment when we assessed FASN expression levels." (PMID 34771486, 2021). "C75, another compound targeting FASN, directly increases FA oxidation and results in apoptosis during S phase in breast cancer cells." (PMID 34775964, 2021).
breast cancer (continued). "For these experiments, we selected Fasnall, a commercially available selective FASN inhibitor that has been shown to exert anti-proliferative effects in several different breast cancer cell lines, including MCF-7, MDA-MB-468, BT474 and SKBR3." (PMID 34769312, 2021). "The relationship between FASN and tumorigenesis of bladder cancer, meningioma, and breast cancer has been reported." (PMID 34879004, 2021). "Based on prior studies, a high expression of FASN can increase the recurrence or metastasis rate of breast cancer." (PMID 34879004, 2021). "FASN is involved in the synthesis of long chain fatty acids and is upregulated in multiple breast cancers." (PMID 34298660, 2021). "Mitochondria in FASN-inhibited cancer cells exist in a primed-for-death state that offers a novel therapeutic opportunity to treat breast cancer by inducing hypersensitization to pro-apoptotic BH3 mimetic drugs." (PMID 34675185, 2021). "Fatty acid synthase (FASN) is likely to be another potential target for inhibiting brain metastasis of breast cancer." (PMID 35071325, 2021). "Reducing FASN expression was observed to increase drug sensitivity in breast cancer cell lines MCF-7 and MDA-MB-468." (PMID 34948368, 2021). "Inhibiting FASN using orlistat can reverse acquired resistance to trastuzumab in breast and ovarian cancer cells, as well as hyper-sensitize breast cancer cells to doxorubicin, docetaxel, paclitaxel, or vinorelbine." (PMID 34298999, 2021). "HER2-driven up-regulation of FASN protein expression in luminal B-like MCF-7/HER2-18 breast cancer cells, however, remained largely unresponsive to the regulatory effects of estradiol and/or tamoxifen." (PMID 33800852, 2021). "Increased de novo FA biosynthesis and FASN upregulation have been observed in breast cancer, melanoma, and hepatocellular carcinoma." (PMID 34606827, 2021). "OPG KO has been shown to inhibit the protein expression of Fatty Acid Synthase (FASN), an essential enzyme that is involved in the fatty acid biosynthetic pathway and is vital for breast cancer existence." (PMID 34066014, 2021). "Fasnall, a selective FASN inhibitor, reduced the proliferation of breast cancer cells and modulated the lipidomic profile of these cells by increasing ceramide levels due to malonyl-CoA accumulation and consequent CPT-1 inhibition." (PMID 33808259, 2021). "Other well-known breast cancer associated genes that were highly expressed in both cell systems included GATA3, GNAS, FASN and NCOA3." (PMID 34680485, 2021). "The study provided a rationale to combine PI3Kα inhibitor with FASN inhibitor for the treatment of breast cancer." (PMID 34373258, 2021). "Fatty acid biosynthesis is also favored by HIF-1 through modulating AKT/mTOR/SREBP-1 signaling in breast cancer, which upregulate the expression of lipogenic enzymes such as FASN." (PMID 34888248, 2021). "ACC 1/2 and FASN expression in breast cancer cells is regulated by diverse growth factors and sex hormones through their corresponding receptors such as PR, ER, androgen receptor, and HER." (PMID 33808259, 2021). "Nonetheless, the results of the meta-analysis confirmed the significant relationship between FASN expression and the outcomes for breast cancer, liver cancer, lung cancer, and gastric cancer (P < 0.05) but not for ovarian cancer (P = 0.998)." (PMID 34879004, 2021). "We postulate FASN as a biological determinant of HER2-driven tamoxifen resistance and FASN inhibition as a novel therapeutic approach to restore tamoxifen sensitivity in endocrine-resistant breast cancer." (PMID 33800852, 2021). "Under pathological conditions, SREBF1 and FASN have been reported to be a pair of metabolically related oncogenes, which have been confirmed to be related to prostate cancer and breast cancer." (PMID 34799559, 2021).
breast cancer (continued). "The abundance of key enzymes required for de novo lipogenesis, including sterol regulatory element-binding protein (SREBP1, SREBP2) and fatty acid synthase (FASN) was reduced in Pparγ1−/− vs. Pparγ1+/+ ErbB2 mammary tumors." (PMID 33946495, 2021). "The close linkage between FASN expression/activity and the acquisition of hormone independence and tamoxifen resistance prompted us to finally investigate the ability of HER2 to activate FASN expression in ER+ breast carcinomas." (PMID 33800852, 2021). "We found that human breast cancer tissues exhibited high FASN SUMOylation compared to normal breast tissue." (PMID 32244364, 2020). "It induced apoptosis by the down-regulation of fatty acid synthase and upregulation of proapoptotic genes and suppressed growth in a xenograft model of breast cancer." (PMID 32756373, 2020). "The expression of fatty acid synthase is closely related to aggressiveness and cell-cycle progression in human cancers, such as breast cancer." (PMID 33256185, 2020). "In this line, we recently reported the specific ability of FASN signaling to regulate the degree of sensitivity of breast cancer cells to estrogen-stimulated breast cancer cell growth and survival." (PMID 33081219, 2020). "In summary, we demonstrated for the first time not only that FASN is SUMOylated, but also that Vermentino leaf extract reduces the ability of breast cancer cells to SUMOylate FASN by lowering the UBC9 protein level." (PMID 32244364, 2020). "In breast cancer cells, FASN overexpression suppressed drug-induced production of ceramide and, thus, reduced caspase 8-mediated apoptosis under treatment with doxorubicin." (PMID 33092283, 2020). "Apart from EGFR, transcriptomic and protein analyses on HER2-amplified breast cancer cell lines showed enhanced FASN expression modulated through the PI3K-dependent pathway." (PMID 32872164, 2020). "This is not surprising, as many downstream growth factors activate PI-3K/AKT and MAPK-ERK1/2 signaling, and FASN activation therefore overlaps with phenotypic traits observed in breast cancer cell lines that overexpress HER2." (PMID 33081219, 2020). "Targeting either ACCA or FASN genes in breast cancer cells using siRNA significantly suppressed fatty acid synthesis, induced apoptosis and arrested cell proliferation, suggesting that ACCA and FASN are equally essential for cell survival." (PMID 33212987, 2020). "Our findings suggest that the homeostatic balance in breast cancer cells favors the second pathway and allows Vermentino-induced FASN degradation to outweigh the induction of FASN mRNA transcription." (PMID 32244364, 2020). "Several studies have shown that FASN is overexpressed in a variety of cancers, such as breast cancer, prostate cancer, ovarian cancer, and CRC." (PMID 33604287, 2020). "It is shown that FASN inhibitors can induce tumor cell apoptosis and sensitize breast cancer cells to chemotherapies." (PMID 32826925, 2020). "FASN is known to be overexpressed across several cancer types, including breast cancer, with expression increasing with tumor stage and predictive of poor prognosis." (PMID 32226926, 2020). "Here, we demonstrated that treatment of breast cancer cells with Vermentino leaf extract altered the levels of FASN and disrupted energetic metabolism, resulting in apoptosis." (PMID 32244364, 2020). "Patuletin inhibited the gene expression and activity of fatty acid synthase and induced the apoptosis of human breast cancer cell line SK-BR-3." (PMID 32756373, 2020). "Inhibition of MAPK pathway and mTOR inhibitor rapamycin both can decrease FASN expression in breast cancer cells." (PMID 33489906, 2020). "MCF-7 cells engineered to stably overexpress HRG (MCF-7/HRG), an in vitro model of tamoxifen/fulvestrant-resistant luminal B-like breast cancer, showed a pronounced up-regulation of FASN gene/FASN protein expression." (PMID 33081219, 2020).
breast cancer (continued). "SUMO2 is shown to protect FASN, where the combination of the protein synthesis inhibitor (cycloheximide) or proteasomal degradation inhibitor (MG132) with SUMO2 silencing, delays FASN degradation in breast cancer cell lines." (PMID 32872164, 2020). "In summary, our data reveal an unforeseen PR-B isoform-specific regulatory action on the cross-talk between prolactin and FASN signaling in luminal breast cancer cells." (PMID 33335078, 2020). "FASN is highly expressed in various breast cancer cell lines, including hormone-independent lines, such as SKBR-3, and hormone dependent lines, such as MCF-7." (PMID 32244364, 2020). "Diosgenin suppresses fatty acid synthase in HER2 overexpressing breast cancer cell line, thus inducing apoptosis and enhancing paclitaxel-induced cytotoxicity." (PMID 32756373, 2020). "In breast cancer, ADP and FASN have been reported to be associated with the immune-biomarker classification, which is a surrogate for molecular subtyping reflecting the different metabolic pathways." (PMID 32103349, 2020). "A high fatty acid synthase (FASN) activity is also involved in ErbB2-induced breast cancer chemoresistance to docetaxel." (PMID 32211323, 2020). "MiR-15a and miR-16-1, through direct binding to the 3 ́UTR of FASN mRNA, inhibited the expression of FASN in breast cancer, reducing proliferation and invasiveness." (PMID 33050166, 2020). "We therefore aimed to evaluate the relationships between prediagnostic erythrocyte membrane fatty acids and breast cancer risk by tumor tissue expression of immuno-inflammatory markers (CD4, CD8, CD20, CD163, COX-2) and fatty acid synthase (FAS)." (PMID 32698885, 2020). "The enhanced expression and increased activity of fatty acid synthase (FASN) have been shown to be early events in breast cancer progression." (PMID 32899149, 2020). "To demonstrate that SUMO2 protects FASN against proteasomal degradation, we treated the breast cancer cell lines with a protein synthesis inhibitor (CHX) and a proteasomal degradation inhibitor (MG132) in combination with SUMO2 silencing." (PMID 32244364, 2020). "Renewed interests in lipid metabolism started after the discovery of FASN, formerly known as oncogenic antigen-519, in breast cancer in 1994." (PMID 32872164, 2020). "FASN has emerged as an important enzyme in HER2+ breast cancers, in particular since HER2 directly phospho-activates FASN protein as well as regulating transcription of FASN mRNA." (PMID 32226926, 2020). "Overall, these findings implicate FASN as a key enabler for endocrine resistance in HRG+/HER2- breast cancer and highlight the therapeutic potential of FASN inhibitors for the treatment of endocrine therapy-resistant luminal-B breast cancer." (PMID 33081219, 2020). "We present evidence that FASN is a key enabler for endocrine resistance in HRG+/HER2− breast cancer and highlight the therapeutic potential of FASN inhibitors for the treatment of endocrine therapy-resistant luminal B-like breast cancer." (PMID 33081219, 2020). "The splicing factor epithelial splicing regulatory protein 1 has been shown to promote endocrine resistance and confer poor prognosis to patients with ER+ breast carcinoma by affecting lipid metabolism including the expression of FASN." (PMID 33081219, 2020). "It has also been reported that the inhibition of FASN results in suppression of the AKT/mTOR signaling pathway in breast cancer cell line." (PMID 31027222, 2019). "Increasing evidences suggest that fatty acid synthase (FAS) plays an important role in human breast cancer." (PMID 31164796, 2019). "Several studies have suggested fatty acid synthase (FASN) as a potential molecular target in the treatment of cancers, especially breast cancer." (PMID 31030489, 2019). "Anticancer effects of PR against breast cancer cells proved via reduction of fatty acid synthase (FASN), reducing HER2 expression and activation in HER2-dependent cells." (PMID 30964898, 2019).